RAB27A (RAB27A, member RAS oncogene family)
Diseases named in the same sentence as RAB27A in open-access papers (continued):
Sharing a sentence is not in itself a finding about the gene and the disease.
Cerebral ischemia (1 paper, 2022). Restriction of arterial blood supply to the brain associated with insufficient oxygenation to support the metabolic requirements of the tissue. "Cerebral ischemia was induced in Rab27a knockout (Rab27a−/−) and wide type (WT) mice by transient middle cerebral artery occlusion (tMCAO)." (PMID 35770324, 2022).
Cirrhosis (1 paper, 2025). A chronic disorder of the liver in which liver tissue becomes scarred and is partially replaced by regenerative nodules and fibrotic tissue resulting in loss of liver function. "In this study, Rab27a expression was upregulated in the livers of patients with cirrhosis and in BDL mice, and its expression tended to be greater than that of Rab27b." (PMID 39804962, 2025).
colorectal tumors (1 paper, 2022). "Concomitantly, the transcript levels of Il33 and Rab27a, both important regulators of mast cells, were reduced and increased, respectively, in the colorectal tumors of Nfe2l3−/− mice." (PMID 35091681, 2022).
cystinosis (1 paper, 2019). Cystinosis is a metabolic disease characterized by an accumulation of cystine inside the lysosomes, causing damage in different organs and tissues, particularly in the kidneys and eyes. "Cystinotic cells are characterized by defective endolysosomal transport, while the induction of vesicular trafficking mechanisms through the upregulation of Rab27a or Rab7 improves vesicular trafficking in cystinosis." (PMID 30774622, 2019).
encephalitis (1 paper, 2024). An acute inflammatory process affecting the brain parenchyma. "Further analyses using Rab27a knockout mice and drugs that regulate Rab27a expression will lead to a better understanding of the importance of Rab27a in the pathogenesis of encephalitis in vivo." (PMID 38715944, 2024).
epilepsy (1 paper, 2019). A brain disorder characterized by episodes of abnormally increased neuronal discharge resulting in transient episodes of sensory or motor neurological dysfunction, or psychic dysfunction. "Alix was reported to be differentially expressed in two epilepsy models and linked to endocytosis and changes to Rab27a levels were present in human epilepsy studies." (PMID 32009885, 2019).
fatty liver (1 paper, 2024). "Related to fatty liver, the blockage of EV secretion by ablation of Rab27a was able to restore normal liver function." (PMID 39107918, 2024).
fibrosarcoma (1 paper, 2026). A malignant mesenchymal fibroblastic neoplasm affecting the soft tissue and bone. "Similarly, inhibition of exosome secretion by Rab27a KD in HT1080 fibrosarcoma cells also led to a decrease in filopodia numbers." (PMID 41532547, 2026).
invasive breast carcinoma (1 paper, 2022). A carcinoma that infiltrates the breast parenchyma. "Additionally, Rab27a expression was significantly lower in the luminal or Her-2 positive subclasses as well as in stage 2 to 4 invasive breast carcinoma than in the normal group." (PMID 35053535, 2022).
ischemia (1 paper, 2022). A hypoperfusion of the BLOOD through an organ or tissue caused by a PATHOLOGIC CONSTRICTION or obstruction of its BLOOD VESSELS, or an absence of BLOOD CIRCULATION. "Our results indicated that Rab27a mediated EXs secretion was important for protecting cerebral microvessels from ischemia‐induced ROS overproduction and EC apoptosis, and the effects were dose‐dependent." (PMID 35770324, 2022). "A recent study in a liver ischemic injury model has suggested that Rab27a mediated liver EXs secretion contributes to hepatic ischemia/reperfusion injury." (PMID 35770324, 2022). "Here, we explored the role of Rab27a in regulating brain EXs secretion, and the effects of Rab27a‐mediated EXs on ischemia evoked cerebral vascular disruption and brain injury." (PMID 35770324, 2022). "In this study, we determined the role of Rab27a in the effects of brain EXs on ischemia‐induced endothelial oxidative stress and apoptosis." (PMID 35770324, 2022). "The major findings of this study are that ischemia could promote Rab27a expression and EXs secretion in peri‐infarct area of mouse brain, and that Rab27a−/− mice were more sensitive to ischemia‐induced cerebral vascular injury." (PMID 35770324, 2022).
ischemic stroke (1 paper, 2022). A stroke disorder caused by obstruction of blood flow to the brain, due to thrombotic (local blood clot formation) or embolic (due to a blood clot or other material traveling from another site) event. "We did not clarify the effects of Rab27a on the secretion of EXs from specific brain cells, such as endothelial cells, astrocytes, and neurons on ischemic stroke." (PMID 35770324, 2022).
kidney cancer (1 paper, 2018). Primary or metastatic malignant neoplasm involving the kidney. "Specifically, POU5F1P1 was correlated with RAB27A, a Ras-related protein in kidney cancer, which is commonly expressed in cancer." (PMID 30287838, 2018).
liver cirrhosis (1 paper, 2018). "Clinically, Rab27a was positively associated with serum alpha-fetoprotein (AFP) level, vascular invasion and liver cirrhosis." (PMID 29725020, 2018). "Clinicopathological analysis showed that Rab27a expression was linked with elevated serum AFP (P = 0.009), vascular invasion (P = 0.031) and liver cirrhosis (P = 0.035)." (PMID 29725020, 2018).
malaria (1 paper, 2012). Malaria is a serious and sometimes fatal disease caused by a parasite that commonly infects a certain type of mosquito which feeds on humans. "The results showed that, compared to the negative control, the live malaria parasite was able to induce an increase in the expression of Rab1a, Rab1b, Rab7a, Rab10, Rab14, Rab20, Rab27a, Rab32 and Rab38." (PMID 22911692, 2012).
metastatic cancers (1 paper, 2022). A carcinoma which has spread from the original site of growth to another anatomic site. "This study highlighted the importance of understanding the mechanisms of Rab27a-mediated metastasis in improving the therapeutic options for metastatic cancers." (PMID 35053535, 2022). "This study also highlighted the importance of understanding the mechanisms of Rab27a-mediated metastasis, which are still largely unknown, in improving the therapeutic options for metastatic cancers." (PMID 35053535, 2022).
myeloid leukemia (1 paper, 2022). A clonal proliferation of myeloid cells and their precursors in the bone marrow, peripheral blood, and spleen. "The authors describe a Rab27a-dependent secretion of EVs and suggest that targeting of Rab27a-dependent secretion of leukemic EVs may be a viable therapeutic approach in myeloid leukemia." (PMID 36498469, 2022).
myocardial infarction (1 paper, 2019). Gross necrosis of the myocardium, as a result of interruption of the blood supply to the area, as in coronary thrombosis. "To determine if the EV secretion is responsible for the cardioprotective effect of hCPCs after myocardial infarction, we injected either sControl-hCPCs or Rab27A KD-hCPCs into the infarct border zone after induction of MI." (PMID 30456736, 2019).
myocarditis (1 paper, 2023). Myocarditis is a condition that is characterized by inflammation of the heart muscle (myocardium). "Our study showed that splenic B and T cells in Rab27a-KO mice with repressed exosomes exhibited a low rate of CVB3 infection, resulting in a high level of specific neutralizing antibody production, a lower viral load in cardiac tissue and minor myocarditis pathogenesis." (PMID 36634130, 2023).
osteoporosis (1 paper, 2024). A condition of reduced bone mass, with decreased cortical thickness and a decrease in the number and size of the trabeculae of cancellous bone (but normal chemical composition), resulting in increased fracture incidence. "Furthermore, a circ_0029463-miR-134-5p-Rab27a network was identified in the regulation of osteoblast differentiation, contributing to an in-depth understanding of the molecular mechanisms underlying osteoporosis." (PMID 38326867, 2024). "RT-qPCR and western blotting were used to detect the expression of circ_0029463, miR-134-5p, and Rab27a in tissues from patients with osteoporosis and in RANKL-induced osteoclasts." (PMID 38326867, 2024). "Elevated expression of circ_0029463 and Rab27a and decreased miR-134-5p expression were observed in the tissues of patients with osteoporosis, and a similar expression pattern was observed in RANKL-induced osteoclasts." (PMID 38326867, 2024). "Elevated mRNA and protein expression of Rab27a detected in patients with osteoporosis and in osteoclasts confirmed our hypothesis (*P < 0.05)." (PMID 38326867, 2024).
Peritoneal Fibrosis (1 paper, 2023). Disorder characterized by a wide range of structural changes in PERITONEUM, resulting from fibrogenic or inflammatory processes. "Blockade of EVs secretion by GW4869 or Rab27a knockdown markedly suppressed PD‐induced fibroblast activation and peritoneal fibrosis." (PMID 37357686, 2023). "Using a mouse model of peritoneal fibrosis induced by PD, we confirmed that injection of TGF‐β‐EVs aggravates PD‐induced peritoneal fibrosis, while impairing EVs secretion by Rab27a knockdown leads to the alleviation of peritoneal fibrosis and improvement of peritoneal dysfunction." (PMID 37357686, 2023).
psoriasis (1 paper, 2025). An autoimmune condition characterized by red, well-delineated plaques with silvery scales that are usually on the extensor surfaces and scalp. "The ROC curves demonstrated that the expression levels of eight Hub Genes—POSTN, CD274, CD24, SERPINB3, CXCL13, SMPD3, BIRC5, and RAB27A—exhibited high accuracy (AUC > 0.9) in classifying the Psoriasis and Control groups." (PMID 40557155, 2025).
pulpitis (1 paper, 2025). Inflammation of the dental pulp. "Overall, our study revealed that Rab27a was upregulated in the MDH of rats with pulpitis and that the exosomes were enriched in IL-1β, indicating increased exosome secretion during the occurrence of pain." (PMID 39987146, 2025). "GW4869 and BBG inhibited Rab27a and IL-1β expression, reducing pulpitis-induced pain." (PMID 39987146, 2025). "Notably, Rab27a protein levels were inversely related to the pain threshold, preliminarily suggesting that exosomes and inflammatory factors are involved in the regulation of pulpitis-induced pain." (PMID 39987146, 2025). "Therefore, we aimed to investigate whether P2X7R regulates microglial Rab27a expression and IL-1β secretion in the experimental pulpitis model." (PMID 39987146, 2025). "In the experimental pulpitis model, GW4869 administration led to pain relief and suppressed the expression of microglial Rab27a." (PMID 39987146, 2025). "The western blot, qRT‒PCR, and double immunofluorescence staining results indicated that BBG decreased Rab27a and IL-1β expression, suggesting that microglial P2X7R-mediated exosome secretion may be a novel mechanism of pulpitis pain." (PMID 39987146, 2025).
Sjögren's syndrome (1 paper, 2017). "In addition, expression of several genes known to be dysregulated in Sjögren's syndrome: CTSS, MHC-II, MMP9, Rab proteins (Rab3D, Rab27A, and Rab27B), IL12α, IFN-γ, TNF-α, and aquaporin 5 (Aq5), and the cholinergic muscarinic M3 receptor (M3R) were quantitatively measured using qPCR." (PMID 28348600, 2017).
status epilepticus (1 paper, 2019). Status epilepticus is defined as a continuous seizure lasting more than 30 min, or two or more seizures without full recovery of consciousness between any of them. "Rab27a and Rab27b expression was also increased after status epilepticus in the ipsilateral CA3 subfield." (PMID 32009885, 2019).
Stroke (1 paper, 2022). Sudden impairment of blood flow to a part of the brain due to occlusion or rupture of an artery to the brain. "Therefore, Rab27a might be implicated in promoting EPCs or astrocytes EXs releasing after stroke and these EXs might contribute to protect against cerebral ischemic injury, which will be detected in our future research work." (PMID 35770324, 2022).
systemic-onset JIA (1 paper, 2008). "In the present study we therefore hypothesized that defective apoptosis in patients with systemic-onset JIA could be due to polymorphisms in the genes PRF1, GZMB, UNC13D, or Rab27a." (PMID 18311812, 2008).
West-Nile encephalitis (1 paper, 2024). "However, elucidation of the involvement of Rab27a in the pathogenesis of West Nile encephalitis in terms of drug development remains challenging." (PMID 38715944, 2024).
tumor (157 papers, 2012 to 2026). "Bladder cancer models show that both Rab27A and B suppression cause the accumulation of tumor suppressive miRNA." (PMID 40722712, 2025). "Hypoxia enhances Rab27a expression in tumour B cells, causes greater release of Cd19+ Ev and hydrolyses ATP to immunosuppressive adenosine via CD39/CD73, weakening CD8+ T cells and reducing the efficacy of chemotherapy." (PMID 38997802, 2024). "Additional role of Rab27a/b in EV biogenesis is described in “Mechanisms of extracellular vesicles associated with communication between tumor and stromal cells” section." (PMID 35927755, 2022). "The RNAs RAB1A, RAB5B, RAB7, and RAB27A, regulators of exosome formation and membrane trafficking are significantly expressed in cells, with interference in Rab27A RNA levels causing reduced exosome production, tumor growth, and metastasis." (PMID 34281588, 2021). "In metastasis assays, loss of Rab27a expression in tumor cells injected into circulation compromised efficient outgrowth of metastatic lesions." (PMID 32355248, 2020). "Exosome shuttling between tumor-associated macrophages and cancer cells has been shown to be modulated by Rab27A/B and this mechanism has been involved to chemotherapy resistance." (PMID 32823947, 2020). "To further confirm that the loss of Rab27a was blocking tumor growth through its role in exosome biogenesis, we repeated the experiments using nSMase2 null cells." (PMID 30951669, 2019). "In contrast, some previous studies showed that reduced exocytosis of miRNAs by Rab27a knockdown caused intracellular upregulation of active tumour-suppressor miRNAs and consequently inhibited tumour growth and invasion." (PMID 29725020, 2018). "The lack of Rab27a was associated with reduced release of exosomes and poor tumor development when compared to cells containing Rab27a, where tumor progression was normal and formed metastasis." (PMID 26393640, 2015). "Cox multi-factor analysis and Kaplan-Meier method suggested Rab27A protein expression (p = 0.012) and tumor differentiation (p = 0.004) were significantly associated with the overall survival of CRC patients." (PMID 26070933, 2015). "Recently, some reports have shown that Rab27a is associated with a series of cancers and that Rab27a expression is closely correlated with tumor progression." (PMID 24587032, 2014). "Moreover, the effect of OT-1 cells was also more pronounced in Rab27a/b-deficient mice with T cell permeable vasculature compared to tumor-bearing dHET littermates." (PMID 40408475, 2025). "Furthermore, depletion of Rab27a decreased PBMC infiltration associated with an increase of tumor cell survival." (PMID 39008536, 2024). "Thus far, the majority of reports associate Rab27a and exosomes mediated communication with an oncogenic function by promoting tumor growth and dissemination." (PMID 37641131, 2023). "However, it is also reported that RAB27A is down-regulated in CRC primary tumor tissues compared with matched adjacent tissues, and down-regulation of RAB27A is associated with advanced TNM stage, distant metastasis, and local recurrence." (PMID 36371494, 2022). "However, neither GW4869 nor Nexinhib-20 are able to inhibit exosome release in other tumor cell lines, although genetic deletion of either nSMase2 or Rab27a leads to tremendous loss of exosome secretion." (PMID 33178688, 2020). "Knocking out Rab27a and nSMase2 in tumor cells causes a loss of PD-L1 in the secreted fraction." (PMID 31647023, 2019). "Loss of either Rab27a or Pd-l1 slowed tumor growth and extended lifespan." (PMID 30951669, 2019). "Thus, our analysis clearly indicates that the high Rab27a expression is associated with tumour progression and metastasis." (PMID 29725020, 2018). "The secretion of exosomes can be promoted by hypoxia and the inhibition of Rab27a has been associated with reduced mobilization of neutrophils, which leads to decreased tumor growth and lung metastasis, demonstrating that Rab27a is involved in cancer progression." (PMID 28098821, 2017).